ATF2 (activating transcription factor 2)
Diseases named in the same sentence as ATF2 in open-access papers (continued):
Sharing a sentence is not in itself a finding about the gene and the disease.
cancer (82 papers, 2008 to 2026). A tumor composed of atypical neoplastic, often pleomorphic cells that invade other tissues. "Although ATF2 plays well-established roles in neurodevelopment, inflammation, and cancer, the mechanisms underlying its nuclear localisation remain poorly characterised." (PMID 41672735, 2026). "The total loss of ATF2 in somatic cells leads to lethality after birth, whereas a partial dysregulation of ATF2 has been associated with cancer development." (PMID 40521202, 2025). "We observed that the cancer driver trophoblast cell surface antigen 2 (TROP2) is one of the key players in the ATF2 network, associated with de-adhesion and migration potential of cancer cells." (PMID 35838828, 2022). "ATF2 mainly located in the nucleus of cancer cells, higher ATF2 level was associated with poor five-year survival of gastric patients, especially in those undergone chemotherapy treatment." (PMID 35641966, 2022). "Evidence suggests that ATF2 is imbalanced in individuals with cancer, whereas complete loss of ATF2 in somatic cells leads to cell death." (PMID 32014006, 2020). "ATF2 dysfunction has been linked to cancer metastasis These proteins are activated by several insults, such as heat shock, UV rays, osmotic shock, cellular DNA damage and their regulation remains obscure." (PMID 32154227, 2020). "Some studies have reported that ATF2 was associated with tumorigenesis and metastasis in several cancers." (PMID 29996942, 2018). "Evidence shows deregulation of ATF2 in cancer cells, whereas complete somatic loss of ATF2 results in cell death." (PMID 29850528, 2018). "ATF2 gene also encodes a TF important for both normal development and cancer progression." (PMID 37816820, 2023). "Together, combined de-regulation of MAPK14 and ATF2 by loss of miR-622 might be specifically beneficial for cancer cells under stress-inducing conditions including chemotherapy." (PMID 33803354, 2021). "Located on chromosome 2q32, ATF2 has been shown in various cancer models to be overexpressed, phosphorylated, and mislocalized subcellularly." (PMID 39633985, 2024). "Numerous evidence indicates that ATF2 can act either as an oncogene or antioncogene in different cancer types depending on its expression level and/or subcellular localization." (PMID 38539832, 2024). "Progress needs to be made to clarify the uncertainty surrounding the exact role of ATF2 and its different behaviors and outcomes in different types of cancers." (PMID 37955015, 2023). "Together, these studies suggest that the spatio-temporal map of β-catenin/TCF-dependent and ATF2-dependent signalling activation during cancer progression is likely to be complex." (PMID 36621522, 2023). "Several studies have suggested the role of ATF2 as an oncogene, promoting cellular proliferation and worsening the outcome of cancers." (PMID 37955015, 2023). "As evident from the studies performed, the exact role of ATF2 in the development of cancer is yet to be fully understood." (PMID 37955015, 2023). "We performed a thorough search on clinicaltrials.gov, which yielded numerous clinical trials in progress/completed to test the impact of certain drugs on ATF2 pathways in the treatment of different types of cancers." (PMID 37955015, 2023). "The in vivo studies nevertheless highlight the potential importance of ATF2-dependent signalling for cancer cell invasion and metastasis." (PMID 36621522, 2023). "We have visualised the activation patterns of β-catenin/TCF-dependent and ATF2-dependent reporters during human cancer cell invasion and metastasis." (PMID 36621522, 2023). "Second, AKT regulates cancer cells by PAK1/ATF2/miR-132 signaling axis and PRKAG3 is a target gene of miR-132." (PMID 36766336, 2023).
cancer (continued). "Here, we use fluorescent β-catenin/TCF-dependent and ATF2-dependent reporters as tools to visualise their activities during cancer cell invasion, intravasation and metastatic lesion formation." (PMID 36621522, 2023). "In malignant hematological cancer, Spatholobus suberectus Dunn, Salvia miltiorrhiza, and Cnidium officinale Makino showed an anti-cancer effect via regulation of miR-657/ATF-2, miR-216b/c-Jun, and miR-211/CHOP, respectively (16a)." (PMID 35321434, 2022). "Although many studies have reported that JNK/ATF2 is involved in cancer metastasis and the EMT process, the molecular mechanism associated with GLUT3 has not yet been studied." (PMID 36009381, 2022). "In cancer, the activating transcription factor 2 (ATF2) has pleiotropic functions in cellular responses to growth stimuli, damage, or inflammation." (PMID 35838828, 2022). "In the present study, we report that GLUT3 promotes the EMT process through TGF-β/JNK/ATF2 signaling pathways, thereby accelerating the cancer progression and invasiveness in CRC cells." (PMID 36009381, 2022). "Although ATF2 expression was elevated in some patients, most cancer cells exhibit low staining that similar with paracancer tissues." (PMID 35641966, 2022). "ATF-2 is highly expressed in many cancer tissues and has been shown to promote the growth of cancer cells." (PMID 35692887, 2022). "For example, ATF2 functions as an oncogene in kinds of cancer types, including breast cancer, melanoma, lung cancer and colorectal cancer." (PMID 34273954, 2021). "Studies have also underlined a role for MAPKα/β kinases and activating transcription factor 2 (ATF2) in antagonizing Her2 signaling early in cancer progression, and a role of ATF2-mediated blockade of β-catenin activity." (PMID 34831167, 2021). "QRT-PCR results showed that ATF2 expression in cancer tissues and cell lines was higher than in normal adjacent tissues and normal bronchial epithelial cell line, respectively." (PMID 33298086, 2020). "Studies have shown that ATF2 acts as an oncogene via promoting target genes transcription in many cancers." (PMID 33298086, 2020). "Initially, bioinformatics analysis using GEPIA algorithm showed that ATF2 was highly expressed in several cancer types." (PMID 33298086, 2020). "In vitro evidence indicated that the upregulation of ATF2 phosphorylation and activity promotes cancer progression via facilitating cell proliferation-related gene expression." (PMID 29178939, 2017). "Some reports also identified ATF2 is a key signal molecule involved in cancer progression and development." (PMID 27588402, 2016). "Here, we found that ATF2 overexpression reverses the inhibitory effects of over-expressed miR-204 on GBM cancer cell proliferation, migration and invasion." (PMID 27588402, 2016). "In mechanistic cell studies, coffee polyphenols change the expression of STAT5B and ATF-2 modifying cyclin D1 levels in cancer cells." (PMID 27608040, 2016). "Cytoplasmic accumulation of ATF-2 resulting in altered mitochondrial membrane potential has been shown to enhance the sensitivity of cancer cells to cytotoxic agents and radiation." (PMID 27764820, 2016). "The growth inhibitory effects of mitochondrial ATF2 were tested in cancer cell lines B16F10, A549, EG7, and LL2." (PMID 25852302, 2015). "To test the contribution of mitochondrial ATF2 to apoptosis, we measured the cytotoxic effect of genotoxic insults on several cancer cell lines by a cell viability analysis while measuring the ATF2 mitochondria accumulation within these cells." (PMID 25852302, 2015). "As ATF2 knockdown also increased apoptosis, we propose ATF2 as a target for combined oxidative stress-based anti-cancer therapies." (PMID 23800081, 2013).
cancer (continued). "It is also clear that some AP1 transcription factors function as procancer proteins (e.g., c-jun, c-fos), while others inhibit cancer development (e.g., JunB, ATF2)." (PMID 23762562, 2013). "The role of ATF2 in cancer progression and outcome is controversial." (PMID 41301032, 2025). "There are contradictions regarding the exact role of ATF2, as some research suggests that it may have a dual role depending on the type of cancer and other affecting factors." (PMID 37955015, 2023). "Although crosstalk between canonical and noncanonical Wnt signalling has been reported previously, this is the first time β-catenin/TCF-dependent and ATF2-dependent branches of signalling have been monitored simultaneously in vivo during cancer cell metastasis." (PMID 36621522, 2023). "Here, using a unique intravital imaging platform and fluorescent reporters, we visualised β-catenin/TCF-dependent and ATF2-dependent signalling activities during human cancer cell invasion, intravasation and metastatic lesion formation in the chick embryo host." (PMID 36621522, 2023). "Additionally, several studies established that TGF-β activation accelerates ATF2 in various types of cancers." (PMID 36009381, 2022). "The cancer driver TROP2 has been identified as a novel transcriptional repressive target of ATF2." (PMID 35838828, 2022). "Aberrant expression or activation of ATF2 regulates the expression of a wide range of genes, which are involved in cell survival, proliferation, growth, apoptosis and DNA damage response, thereby playing an important role in cancer progression." (PMID 34273954, 2021). "Previous studies have reported that ATF2 is involved in the pathobiology of numerous cancers." (PMID 33298086, 2020). "Indeed, many of these microbes’ abundance correlated with the increased activity of cancer-associated pathways, including the AKT, ERK, EZH2, and ATF2 pathways." (PMID 32575865, 2020). "Cisplatin treatment induced phosphorylation of ATF2 in cancer cells." (PMID 29108284, 2017). "Emerging evidence has indicated that ATF2 exerts paradoxical roles in different cancers." (PMID 27377902, 2016). "Herein, we clearly show that ATF2 can interact with VDAC1 to disrupt the HK1/VDAC complex in various cancer cells, suggesting that ATF2 might bind to VDAC1 in competing with HK1 and thus promote cytochrome c release." (PMID 25852302, 2015). "ATF2 expression has been correlated with maintenance of a cancer cell phenotype." (PMID 22140479, 2011). "Moreover, ATF2 is considered as a major driver of cancer progression and might serve as a promising future therapeutic target in HCC and other types of cancer." (PMID 33803354, 2021). "Therefore, the role of ATF2 may depend on cancer-specific contexts and its role in RCC remains unknown." (PMID 27377902, 2016). "Cytoplasmic accumulation of ATF-2 and altered mitochondrial membrane potential have been shown to enhance the sensitivity of cancer cells to cytotoxic agents and radiation, leading us to hypothesize that rigosertib could act synergistically in combination with HNSCC standard-of-care therapies." (PMID 27764820, 2016). "This may emphasize the important role of ATF2 in DNA damage checkpoint control in cancer." (PMID 23800081, 2013). "Furthermore, novel studies led to the conclusion that ATF2 may play an important role in tumorigenesis, suggesting ATF2 as a cancer drug target." (PMID 23800081, 2013).
cancer (continued). "Additionally, MAPK pathways modulate protein expression by phosphorylating ATF-2, a basic/leucine zipper (bZIP) motif-containing member of the leucine zipper family of DNA-binding proteins, with research primarily centered on its roles in cancer and inflammation." (PMID 40823018, 2025). "Of the 740 analyzed transcripts involved in various steps of cancer progression, we focused on genes that were significantly deregulated in both HCT116 ATF2-KO clones compared to the wildtype (adjusted P < 0.01 and absolute (log2(FC) > 1))." (PMID 35838828, 2022). "Through gene set enrichment analysis (GSEA), we found that the significantly differentially expressed genes were significantly enriched in ATF2- and ERBB2-related cancer genes." (PMID 35646860, 2022). "Similar in its mode of action to MALAT1 and NEAT1, LncRNA UCA1 upregulates cancer-promoting Sirt1, CXCR4, and activating transcription factor-2 (ATF-2) through sponging of miR-204." (PMID 35159022, 2022). "The high ectopic expression of PRCC made cancer cells insensitive to DNA damage, and enhanced the heterogeneity of HCC cells by inhibiting the JNK/ATM/ATR/ATF2 axis." (PMID 34715922, 2021). "Those events occurred on pre-mRNA of 56 genes including well-known cancer-related genes PTPRC, IKBKB and HRAS, and genes coding for transcription factors ILF2, ATF2 and EYA3." (PMID 34543356, 2021). "Unfortunately, various disorders are also associated with altered ATF2 expression and/or its phosphorylation, and ATF2-coupled pathological processes may affect, among others the kidneys, the nervous system, and the pancreas and may contribute to the development of different types of cancer." (PMID 34302199, 2021). "Activating transcription factor 2 (ATF2), a member of the activator protein 1 (AP-1) transcription factor family, has been shown to be involved in the pathobiology of numerous cancers." (PMID 33298086, 2020). "Here, we report the increased expression of AP-1, ATF2, REST, and EGR3, all transcription factors involved in cancer cell invasive behavior." (PMID 30813636, 2019). "Activating transcription factor 2 (ATF2) is a basic helix-loop-helix transcription factor, which has been shown to participate in the pathobiology of numerous cancers." (PMID 27377902, 2016). "This is in agreement with our finding that a low ATF2 level downregulates COX2 transcription and hence suppresses cancer cell invasion." (PMID 23878598, 2013). "We predict the differential expression of several transcription regulator genes (including HSF2, ARNT, MEF2A, ATF2 and YY1) that are strongly related to the cancer grade." (PMID 20025723, 2009). "Similarly, for INMON, FOXO3 and IRF5 were common TFs in healthy and early-stage tissues (e.g., BRCA1-mut); specifically, PRDM4 was the TF in precancer stages (e.g., Goiters and HT) while ATF2 and RUNX1 were enriched in cancers (e.g., ESCC and IDC)." (PMID 38645221, 2024). "Similarly, the cancer cells that are responsible for metastatic lesion invasion show reduced β-catenin/TCF-dependent signalling, while maintaining sufficient levels of ATF2-dependent activity (Fig. 7Fiii)." (PMID 36621522, 2023). "The typical cellular localization patterns of MAPK14 and ATF2 were also confirmed in non-HCC cancer cells." (PMID 33803354, 2021). "Overall, these findings provide scientific evidence that miR657 is an onco-miRNA targeting the ER stress signal pathway and SSD induces apoptosis via the inhibition of miR-657, ROS, and the activation of p-ATF2 and CHOP as a potent anti-cancer agent for myeloid-originated hematological cancer." (PMID 30696076, 2019).
cancer (continued). "Thus, deregulation of AXL/eIF4E in drug-resistant cancer cells invokes ER stress, which in turn activates a stress-relief UPR mediated by the PERK/JNK/ATF2 cascade." (PMID 31431614, 2019). "Furthermore, BaP and metabolites were also shown to relate to HCC by activating cancer-related transcription factor networks involved in proliferation and inflammation (e.g., AP-1, HIF-1, ATF-2 and NF-κβ)." (PMID 26238291, 2016). "Furthermore, the mechanisms of CIP2A activation and overexpression in cancer cells has been investigated by several other studies in which E2F1, ETS1, and ATF2 were found to directly bind to the CIP2A promoter and further stimulate CIP2A transcription." (PMID 24884612, 2014). "Furthermore, ATF2 activated through the JNK1/2 pathway plays a role in attenuating ferroptosis induced by treatments with BETi (inhibitors of bromo- and extra-terminal domain) in cancer cells and this was mediated by increased expression of NRF2." (PMID 38539832, 2024). "Nevertheless, we wished to determine whether an ATF2-dependent reporter could be used as a readout for noncanonical Wnt signalling in HT1080 cells during cancer cell invasion in vivo, given that, to our knowledge, this has not been studied previously." (PMID 36621522, 2023). "Indeed, according to our model, downregulation of Wnt/β-catenin activity alone could lead to enhanced noncanonical activities, including ATF2-dependent activity, and increased cancer cell invasion and intravasation." (PMID 36621522, 2023).